CXCL16 (C-X-C motif chemokine ligand 16)
Diseases named in the same sentence as CXCL16 in open-access papers (continued):
Sharing a sentence is not in itself a finding about the gene and the disease.
colorectal cancer (19 papers, 2014 to 2025). A primary or metastatic malignant neoplasm that affects the colon or rectum. "On the other hand, a higher expression of CXCL16 is associated with better overall survival in patients with colorectal cancer, gastric carcinoma, non-small cell lung cancer, and renal cell carcinoma." (PMID 33800554, 2021). "In colorectal cancer patients, high preoperative levels of serum CXCL16 were associated with recurring liver metastasis and a poor prognosis." (PMID 27471636, 2016). "That is why the aim of our study was an effort to elucidate and evaluate the utility of selected CXC-chemokines determination (CXCL5, CXCL14 and CXCL16) in patients with colorectal cancer compared to healthy control." (PMID 37848726, 2023). "Remarkably, an earlier report suggested that apoptosis is induced by CXCL16 in colorectal cancer liver metastasis." (PMID 35335970, 2022). "We were able to find only one report describing CXCL16-mediating tumor-inhibiting function in colorectal cancer (CRC)." (PMID 36686729, 2022). "The role of CXCL16 in the recruitment of T-cells has been described in inflammatory valvular heart disease, psoriasis pathogenesis, rheumatoid joints, colorectal cancer, hepatic ischemia-reperfusion injury, and interstitial rejection of renal allograft." (PMID 35335970, 2022). "For example, increased infiltration of CD8+ and CD4+ T cells was associated with CXCL16 and its receptor CXCR6 expression in colorectal cancers." (PMID 30774761, 2019). "For example, CXCL16 expression was consistently up-regulated in colorectal cancer tissues than in normal mucosa, and the high CXCL16 expression patients showed significantly better prognosis than the low expression patients." (PMID 31262330, 2019). "In a mouse model of colorectal cancer, CXCL16 inhibited liver metastasis via recruitment of CXCR6 expressing T cells and iNKT cells." (PMID 27471636, 2016). "In colorectal cancer, high tumor CXCL16 expression has been correlated with a favorable prognosis, while high sCXCL16 is linked to recurrence." (PMID 26021984, 2015). "In this study, we focused on a membrane-bound chemokine CXCL16, which has shown a correlation with a good prognosis for colorectal cancer (CRC) patients." (PMID 25495942, 2014). "Studies on colorectal cancer and nasopharyngeal carcinoma have shown that the level of CXCL16 expression is associated with tumor infiltration by anti-cancer TIL, and so CXCL16 can be used in cancer therapy." (PMID 33800554, 2021). "CXCL16 may also be a serum marker of worse overall survival for cancer patients with colorectal cancer, gastrointestinal stromal tumors, or ovarian cancer." (PMID 33800554, 2021). "In colorectal cancer, CXCL16 secreted by cancer cells recruits CD4+ and CD8+ T cells." (PMID 33763372, 2021). "CXCL16/SR-PSOX has been described as a positive prognostic marker in renal and in colorectal carcinoma, where tumors with high CXCL16/SR-PSOX expression had an increased number of CD4 and CD8 T cells and a better prognosis than the weak CXCL16/SR-PSOX expression group." (PMID 26062132, 2015). "In co-culture of colorectal cancer SL4 cells with RAW 264.7 cells, CXCL16 induced tumor cell apoptosis mediated by TNFα-expressing macrophages." (PMID 36686729, 2022). "This study’s main purpose was to determine plasma CXCL16 levels after minimally invasive colorectal resection (MICR) for colorectal cancer (CRC); an adjunct study assessed wound fluid (WF) and plasma CXCL16 levels in a separate group of CRC patients." (PMID 29981574, 2018). "CXCL16 expression is also strongly correlated with increased tumor infiltration of CD4+ and CD8+ T cells in colorectal cancer, and improved survival in cancer patients." (PMID 27471636, 2016). "Several pro-angiogenic (VEGF, Ang-2, PIGF, sVCAM-1, MCP-1, MMP-3, CHI3L1, IL-8 and CXCL16) and ECM-degrading (MMP-2 and MMP-7) proteins are known to be elevated after colorectal cancer resection, but in relation to postoperative complications such research remain scarce." (PMID 39167197, 2024).
hepatocellular carcinoma (18 papers, 2010 to 2025). A malignant tumor that arises from hepatocytes. "Suppression of CXCR6, a receptor for CXCL16, has been found to reduce tumor angiogenesis in a hepatocellular carcinoma xenograft mouse model." (PMID 38172124, 2024). "For example, release of the chemokine CXCL16 by stimulated murine and human hepatoma, endothelial, or stellate cells remained unaffected." (PMID 33814981, 2021). "It has been demonstrated that the CXCL-16/CXCR6 axis promotes hepatocellular carcinoma invasiveness and induces a proinflammatory tumor environment for metastasis in various cancer types." (PMID 30483898, 2019). "Similar roles for CXCL9, CXCL13 and CXCL16 in T- and B-cell recruitment have been suggested in other models of liver disease including chronic Hepatitis C, Hepatocellular Carcinoma, Primary Biliary Cirrhosis and Primary Sclerosing Choliangitis." (PMID 20161726, 2010). "CXCL16 activity may also occur in hypoxic regions, where the expression of this chemokine is upregulated by chronic hypoxia, as shown in hepatocellular carcinoma Huh-7 and HepG2 cells." (PMID 33800554, 2021). "In hepatocellular carcinoma, the gut microbiome uses bile acids as messengers to regulate chemokine CXCL16 levels on liver sinusoidal endothelial cells in order to control the accumulation of CXCR6+ hepatic natural killer T (NKT) cells that keep liver tumors at bay." (PMID 33262469, 2021). "Notably, in hepatocellular carcinoma models, primary bile acids can upregulate C-X-C motif chemokine ligand 16 (CXCL16) expression on liver sinusoidal endothelial cells (LSECs), thereby recruiting and activating Natural Killer T (NKT) cells to enhance antitumor immunity." (PMID 41357193, 2025). "In a hepatocellular carcinoma xenograft mouse model, suppression of CXCR6, a receptor for CXCL16, reduced tumor angiogenesis." (PMID 31527616, 2019). "In eight hepatoma cells, CXCR6 and its ligand CXCL16 are consistently expressed, and elevated expression of CXCR6 promotes HCC invasiveness and is associated with poor outcomes of patients." (PMID 23941552, 2013). "Also, CXCL16 increases CXC motif chemokine ligand 8 (CXCL8)/IL-8 expression in prostate PC3 and C4-2B cancer cells and in hepatocellular carcinoma SK-HEP-1 and HCCLM3 cells." (PMID 33800554, 2021). "For this reason, the use of CXCL16-neutralizing antibody or an antagonist of the CXCR6 receptor inhibits tumor progression in in vitro experiments, in particular in pancreatic ductal adenocarcinoma and hepatocellular carcinoma." (PMID 33800554, 2021). "As per studies, CXCL16 could help to locally sustain the cytotoxic T lymphocyte (CTL) response for effective tumor control and the overexpression of CCL14 could inhibit the proliferation of hepatoma cells and promote apoptosis." (PMID 37711200, 2023).
liver cancer (18 papers, 2009 to 2025). An epithelial or non-epithelial malignant neoplasm that arises from the liver. "We found a bias for high CXCL16 expression in cancers associated with inflammation: ovary, breast, prostate, colon and liver cancers." (PMID 19690611, 2009). "Also, T-β-MCA has been implicated in the liver cancer immunity through its role in CXCL16 production, which promotes natural killer T cell migration within the liver, and protects from HCC." (PMID 38157359, 2023). "Interestingly, activation of NKT cells is also dependent on CXCR6/CXCL16 interaction, as deficiency of CXCR6 or neutralization of CXCL16 cause hepatic cancer to deteriorate." (PMID 36389715, 2022). "In liver cancer, bile acid metabolism changes caused by gut microbiota regulates the expression of CXCL16 and recruits CXCL16-mediated natural killer T (NKT) cells, which could control the liver tumor growth." (PMID 34267748, 2021). "Similarly, abnormally high expression levels of CXCR6 and CXCL16 are found to be closely related to tumor proliferation and metastasis, and have been reported to be associated with human ovarian cancer and the metastasis of liver cancer cells." (PMID 33381455, 2020). "In conclusion, the intestinal microbiome can use bile acids as messengers to regulate the level of CXCL16 and influence the growth of liver cancer by controlling the aggregation of CXCR6+ liver NKT cells." (PMID 38169949, 2023). "Another study reported that co-cultures of liver cancer cells or patient xenografts organoids with endothelial cells upregulated CXCL16, IL-8, MCP-1, and TNF-α expression and secretion." (PMID 37887354, 2023). "CXCL16 is highly expressed in many cancers, including ovarian, breast, prostate, colon, and liver cancers, and the expression of CXCL16/CXCR6 correlates with lymph node metastasis in epithelial ovarian carcinoma 52,53." (PMID 31892988, 2020). "In contrast, high expression of CXCR6 and CXCL16 in mammary or liver cancers correlated with reduced proliferation and invasiveness." (PMID 28267793, 2017). "Inhibition of bile acid (BA)-converting Clostridium species that are responsible for converting primary BAs to secondary BAs can increase the expression of CXCL16 on LSECs to attract the infiltration of hepatic CXCR6+ NKT cells to inhibit liver cancer progression." (PMID 38283696, 2024). "In addition, secondary bile acids can also inhibit the activation of NKT cells by inhibiting the expression of CXCL16 in liver sinusoidal endothelial cells, and promote liver cancer and cancer liver metastasis." (PMID 38169949, 2023). "Besides, studies have shown that bile acids can affect the expression of chemokine CXCL16, and then affect the infiltration of natural killer T cells in liver cancer through intestines-liver axis, and then affect the biological behavior of tumor." (PMID 34901155, 2021). "A dysregulated primary to secondary BA ratio has been observed in liver cancer patients, in which chenodeoxycholic acid (primary BA) levels are positively correlated with CXCL16 expression, and glycolithocholate (secondary BA) levels are negatively correlated with CXCL16 expression." (PMID 35327352, 2022).
vitiligo (18 papers, 2019 to 2025). Generalized well circumscribed patches of leukoderma that are generally distributed over symmetric body locations and is due to autoimmune destruction of melanocytes. "More recent meta-analysis data show that CXCL9, CXCL10, CCL5, CXCL8 (IL-8), CXCL12, and CXCL16 can serve as diagnostic blood biomarkers for vitiligo." (PMID 38673994, 2024). "Tissue-resident memory (TRM) T cells in mouse and human melanoma-associated vitiligo skin form large lymphoid aggregates with CXCL16-expressing dendritic cells." (PMID 34362825, 2021). "CXCL16 levels are elevated in the peripheral blood of vitiligo patients and decline after treatment that effectively repigments lesional sites." (PMID 40361040, 2025). "Oxidative stress (H2O2) is correlated with CXCL16 mRNA levels in the skin of progressive vitiligo patients and serum CXCL16 decreases following successful therapy." (PMID 36911664, 2023). "Circulating CXCL16 levels were elevated in vitiligo in 2 studies (40 vitiligo patients and 24 healthy controls)." (PMID 36911664, 2023). "In connection with the other fundamental pathogenic mechanism already mentioned, oxidative stress in patients with vitiligo leads to an increase in local levels of the cytokine CXCL16 due to the activation of the UPR in stressed keratinocytes." (PMID 38139134, 2023). "This increased expression of CXCL16 leads to the recruitment of CD8+ CXCR6+ T cells, whose expression is accompanied by loss of melanocytes in vitiligo patients." (PMID 38139134, 2023). "A more recent study noticed that the expression of CXCL16 in the serum of vitiligo patients was positively correlated with ROS level." (PMID 35096274, 2022). "Under the promoted CXCL16 production, the cutaneous infiltration of CXCR6+ CD8+ T cells was increased in vitiligo perilesional skin, leading to melanocyte loss in vitiligo lesions." (PMID 35096274, 2022). "The High-mobility group protein B1 (HMGB1), as a pro-inflammation factor in the downstream of NLRP3 inflammasome, has been proved to facilitate the secretion of IL-8 and CXCL16 in keratinocytes which contributed remarkably to the pathogenesis of vitiligo." (PMID 32754591, 2020). "Oxidative stress can induce the dysfunction of keratinocytes, and then, stressed keratinocytes secrete CXCL16 to recruit CD8+ T cells to lesional sites to promote vitiligo." (PMID 31885781, 2019). "Additionally, impaired autophagy increases CXCL16 secretion from keratinocytes, suggesting the involvement of impaired and altered autophagy in vitiligo pathogenesis." (PMID 38673994, 2024). "Then, by using Poly(I:C) to imitate virus invasion, we clarified that virus invasion significantly activated MDA5 and further potentiated the keratinocyte-derived CXCL10 and CXCL16 which are the two vital chemokines for the cutaneous infiltration of CD8+ T cells in vitiligo." (PMID 32532953, 2020). "Besides, in vitro assay verified that neutralizing CXCL16 in the supernatant of H2O2-treated primary keratinocytes significantly decreases the migration of CD8+ T cells sorted from vitiligo patients." (PMID 32532953, 2020). "Intriguingly, the study reported that activating the UPR in keratinocytes can promote CXCL16 upregulation and drive CD8+ T cells’ skin transport in vitiligo patients." (PMID 41169396, 2025). "In patients with vitiligo, activation of IRE1α-XBP1 signalling increases CD8+ T-cell recruitment by upregulating CXCL16 expression, thereby leading to melanocyte-specific autoimmune responses and depigmentation of the skin." (PMID 38297380, 2024). "Taken together, these studies reinforce the role of keratinocyte-derived CXCL16 in the activation of melanocyte-specific autoimmunity, especially in the context of oxidative stress, indicating that inhibition of this chemotactic axis may be a promising treatment option for vitiligo patients." (PMID 35096274, 2022).
vitiligo (continued). "C-X-C motif chemokine ligand 16 (CXCL16) levels are enhanced by IRE1α/XBP1s signaling in stressed keratinocytes, which are involved in recruiting CD8+ T cells to vitiligo lesions." (PMID 36439174, 2022). "In vitiligo, RAGE seems to be overexpressed in the epidermal layers: its blockade with specific antibodies reduces the release of CXCL16 and IL-8, which prompt the chemotaxis of T-cells." (PMID 33435332, 2021). "In summary, our results demonstrate that MDA5 signaling orchestrates the aberrant skin immunity engaging in melanocyte death via mediating CXCL10 and CXCL16 secretion, which supports MDA5 as a potential therapeutic target for vitiligo under virus invasion." (PMID 32532953, 2020). "More importantly, HMGB1 activates NF-κB signalling and then promotes the production of chemokines, including CXC chemokine ligand 16 (CXCL16) and interleukin-8 (IL-8), thereby inducing CD8+ T cell migration and establishing an immune microenvironment unique to vitiligo." (PMID 40308590, 2025). "CXCL16 can be secreted from keratinocytes, dendritic cells, and even Langerhans cells, and functions as a chemokine by binding to its receptor CXCR6 to mediate homing of CD8 + T cells in vitiligo skin." (PMID 40361040, 2025). "CXCL16, derived from keratinocytes under oxidative stress, could also recruit CD8+ T cells to the epidermis, resulting in melanocyte damage in vitiligo." (PMID 41169396, 2025). "Moreover, the overexpression of CXCL16, a mediator of the innate immunity, on altered keratinocytes in response to oxidative stress promotes CD8+ T cell trafficking in vitiligo." (PMID 35329832, 2022). "Intriguingly, of the mentioned cytokines and chemokines, many are reported to be biomarkers for vitiligo like IL‐1β, CXCL9, CXCL10, and CXCL16, which might aid vitiligo diagnosis and prognosis." (PMID 33200838, 2021). "Alternatively, CXCL16 secreted by CD11c+ cells may continuously recruit CD8 TRM cells to the clusters and areas of vitiligo through CXCR6." (PMID 34362825, 2021). "Furthermore, IFIH1, encoding intracellular virus sensor MDA5, has been identified as a vitiligo susceptibility gene capable of inducing secretion of CXCL10 and CXCL16 from keratinocytes and inducing infiltration of CD8+ T cells in vitiligo." (PMID 33936032, 2021). "In the present study, we initially manifested that the expression of MDA5 and anti-CMV IgM was upregulated in some progressive vitiligo, which was accompanied by the increment of the mRNA levels of CXCL10, CXCL16 in the epidermis and the infiltration quantity of CD8+ T in the skin tissues." (PMID 32532953, 2020). "As gene analysis on cells isolated from lesional and nonlesional skin of vitiligo has identified CXCL16 and CXCR6 in the pathogenesis of the disease, the role of the CXCL16-CXCR6 axis in vitiligo is better appreciated in recent studies." (PMID 35096274, 2022).